SOX9 (SRY-box transcription factor 9)
Diseases named in the same sentence as SOX9 in open-access papers (continued):
Sharing a sentence is not in itself a finding about the gene and the disease.
melanoma (continued). "DNA methylation of SOX9 gene upstream regions has been documented in several cancer types, including bladder cancer, cervical cancer, and melanoma, and SOX9 expression can be silenced by SOX9 DNA methylation in bladder and melanoma models." (PMID 40179020, 2025). "SOX9 is a transcription factor that plays a role in neural crest specification and its overexpression in melanoma cell lines has been shown to induce cell cycle arrest through a p21-dependent mechanism." (PMID 41465475, 2025). "Mesenchymal and neural-crest tumor states (MART1− NGFR+ and/or SOX9+) emerged only in invasive melanomas, including RGP and VGP regions." (PMID 40667360, 2025). "The results demonstrate a significant upregulation in the expression levels of the examined marker genes, excluding sox9, as melanoma develops." (PMID 39659584, 2024). "Correlating with slower tumor growth rates of YUMM2.1-dHLH tumors, the percentage of Ki67+ melanoma cells (Sox9+ or Sox10+ cells) were lower in YUMM2.1-dHLH compared to YUMM2.1-WT tumors." (PMID 38245503, 2024). "We found that AP-1 factors, particularly c-JUN and JUNB were also induced by WT-Bmal1 or dHLH-Bmal1 in the human WM3629 melanoma cells with corresponding increase in SOX9 and decrease in SOX10 levels." (PMID 38245503, 2024). "This antagonistic relationship between SOX10 and SOX9 also appears to extend to other cancers, i.e., resulting in melanoma progression upon reduced expression of SOX10." (PMID 39285246, 2024). "PITX1 binds to the promoter region of SOX9, promoting its transcription and thus suppressing the growth and proliferation of melanoma by inhibiting SOX10 and SAMMSON." (PMID 37841446, 2023). "This study disclosed a significant co-expression of SOX10, SOX9, and neistin in early primary melanoma." (PMID 38132479, 2023). "EGFR, along with SOX9, are upregulated in melanoma cells with undifferentiated phenotypes, and their expressions are induced by the loss of SOX10." (PMID 35406721, 2022). "TEAD knockdown inhibits invasion in melanoma cells with an invasive phenotype and downregulates TEAD target genes, including SOX9/Hippo pathway genes, and many other genes linked to metastases promotion." (PMID 35406721, 2022). "Conversely, in bladder cancer and melanoma, hypermethylation of the SOX9 promoter leads to SOX9 silencing." (PMID 36114905, 2022). "Taken together, these findings suggest that PITX1 plays a suppressor role in the proliferative phenotype of melanoma cells as an upstream transcription factor of SOX9 and SOX10." (PMID 34526609, 2021). "This is reminiscent of melanoma cells displaying reduced SOX10 levels, which is associated with increased expression of SOX9, another factor involved in NC development, and increased invasiveness." (PMID 34417458, 2021). "In primary melanoma tissue, we found a positive correlation between SOX9 and PITX1 expression in the TCGA data set." (PMID 34526609, 2021). "In contrast, SOX9 is expressed in normal human melanocytes but its expression is downregulated in nevi and melanoma." (PMID 34526609, 2021). "We have reported that PITX1 directly regulated SOX9 through targeting the promoter region in melanoma cells." (PMID 34526609, 2021). "Expression levels of SOX9 were negatively correlated with those of SOX10 levels in the TCGA primary melanoma tissue data set; however, it is lower than the GEO data set." (PMID 34526609, 2021). "SOX9 has been demonstrated to regulate resistance to T-cell-mediated killing in melanoma cells through CEACAM1, a pivotal protein in crosstalk between cancer cells and immune environment." (PMID 34094897, 2021). "For melanoma cells, it was reported that the overexpression of SOX9 can also promote the invasiveness of the parental melanoma cells by modulating the expression of various MMPs." (PMID 33076370, 2020). "Our recent studies revealed that a low level of SOX9 expression inhibited melanoma growth and metastasis, whereas high SOX9 promoted melanoma progression." (PMID 32214200, 2020).
melanoma (continued). "In contrast, elevation of SOX9 expression is highly effective in restoring melanoma invasiveness in SOX10 KD cells." (PMID 30642390, 2019). "SOX10 or high SOX9 expression regulates melanoma mesenchymal migration through the NEDD9-mediated focal adhesion dynamics and Rho GTPase signaling." (PMID 30642390, 2019). "Lastly, SOX10 or high SOX9 regulates focal adhesion turnover and Rho GTPase signaling to promote mesenchymal migration of melanoma cells." (PMID 30642390, 2019). "We selected two melanoma cell lines with low expression of SOX9, but high expression of SOX10 (cell lines Malme-3M and UACC-62)." (PMID 30683138, 2019). "Lastly, SOX10 or high SOX9 expression mediates melanoma cell migration through the NEDD9-regulated focal adhesion dynamics and Rho GTPase signaling." (PMID 30642390, 2019). "Here we demonstrate that SOX10 is expressed in melanocytic nevus, primary cutaneous, and invasive melanomas where SOX9 exhibits unique but overlapping expression with SOX10." (PMID 30642390, 2019). "It will be worth to perform RNAseq in melanoma cells expressing various levels of SOX9 expression in order to unravel the sets of downstream target genes responsible for the anti-metastatic and the pro-metastatic effects." (PMID 30642390, 2019). "Based on our findings together with others, we propose that SOX10 inhibits SOX9 and/or SOX9 promoter is methylated that maintain SOX9 expression at low or sub-optimal level in primary melanoma." (PMID 30642390, 2019). "In contrast, further elevation of SOX9 dosage corresponding to high SOX9 in metastatic melanoma specimens lead to opposite effects on p21 and NEDD9 expression with enhanced tumor growth and metastasis as well as induction of MMPs expression." (PMID 30642390, 2019). "SOX10 levels were higher in all melanoma cell lines than in normal human melanocytes (HEMa-LP), whereas SOX9 expression was low in all these cell lines." (PMID 30642390, 2019). "This explains why low levels of SOX9 expression are negatively correlated with NEDD9 in most primary melanoma specimens." (PMID 30642390, 2019). "These in vitro findings suggest that high level of SOX9 expression is metastatic/tumorigenic in melanoma cells." (PMID 30642390, 2019). "High SOX9 expression was predominantly detected in patients with distant melanoma metastases whereas SOX10 was present in the different stages of melanoma." (PMID 30642390, 2019). "Its role in other cancers remains controversial, for example, in melanoma, Sox9 has been reported to be protective or represent a negative prognostic factor." (PMID 30622340, 2019). "Compensatory upregulation of SOX9 expression in SOX10-inhibited melanoma cells reduced growth and migratory capacity, partly due to elevated expression of cyclin-dependent kinase inhibitor p21 and lack of NEDD9 induction." (PMID 30642390, 2019). "In agreement with this, we performed qPCR for SOX9 on a cohort of melanocytic nevi and primary melanomas and the majority of which remained at the basal level of expression." (PMID 30642390, 2019). "Altogether, our findings demonstrate that distinct transcriptional targets of SOX9 at different levels of expression confer melanomas with various cellular properties." (PMID 30642390, 2019). "Investigating ATRA response mechanisms, we focused on PRAME, recently reported as a dominant repressor of RAR signaling in AML, and SOX9, a transcription factor significantly down-regulated in melanoma specimens." (PMID 29484133, 2018). "SOX10 inactivation induces a marked upmodulation of SOX9, with consequent induction of cell cycle arrest and melanoma cell death." (PMID 29156643, 2017). "In melanoma SOX9 is necessary to switch melanoma from a proliferative state to an invasive one whereas it regulates about 10% of the genes that define the invasive phenotype gene set." (PMID 29121666, 2017). "Surprisingly, none of the deletions had any impact on the suppressive effect of SOX9 on the CEACAM1 promoter in two different melanoma cell lines." (PMID 26885752, 2016).
melanoma (continued). "A SOX10-low state is associated with reduced cell proliferation and engagement of EMT-like processes in melanoma to promote more invasive phenotypes - a state maintained, in part, through mutual-antagonism with the closely related transcription factor SOX9." (PMID 27852308, 2016). "The shorter construct was still similarly inhibited by SOX9, as tested in luciferase reporter assays in three melanoma cell lines." (PMID 26885752, 2016). "Remarkably, silencing of SOX9 rendered all tested melanoma lines significantly more resistant to killing by TIL14 cells, as compared to the control." (PMID 26885752, 2016). "In conclusion, we show that SOX9 regulates CEACAM1 expression in melanoma cells, and thereby their immune resistance." (PMID 26885752, 2016). "Luciferase reporter assays were repeated with the mutated or wild-type (WT) pCEACAM1 constructs, which were co-transfected with SOX9 or an empty vector, in three melanoma cell lines." (PMID 26885752, 2016). "SOX9 was efficiently silenced in all melanoma lines tested except for A375, using SOX9-specific siRNA as compared to control scrambled RNA sequence." (PMID 26885752, 2016). "In the present study, we found that Met is rather expressed in melanoma cells characterized by more differentiated phenotypes such as pigmentation, lower Kit and Sox9 expression." (PMID 27683122, 2016). "SOX9 induced a remarkable inhibition in luciferase activity, as compared to control, in all melanoma cell lines tested." (PMID 26885752, 2016). "The effect of manipulations in SOX9 expression on CEACAM1 was tested in several melanoma cell cultures." (PMID 26885752, 2016). "SOX9 expression was selectively silenced in several melanoma cells with an anti-SOX9 siRNA or a scrambled sequence as a control." (PMID 26885752, 2016). "The luciferase reporter construct was co-transfected with SOX9 or with an empty vector as a control into different melanoma lines." (PMID 26885752, 2016). "In differentiation-supported conditions, TAFH RNAi-treated melanoma cells started to express chondrogenic-specific SOX9, NKX3.2 and RUNX2; adipogenic PPARG; and neurogenic NTRK2, NF-M and SYP mRNAs at 48 h post-stimulation of differentiation." (PMID 27499390, 2016). "5-Aza-2-deoxycytidine treatment of various melanoma cell lines was shown to increase SOX9 expression and induce expression of p27 and p21." (PMID 25885555, 2015). "In conclusion, we found SOX9 to be regulated by DNA methylation, and high SOX9 expression leads to poor survival in melanoma patients due to the activation of EMT-like genes and the downregulation of potential tumor suppressor genes in melanoma cells." (PMID 25885555, 2015). "The majority of CpGs in both regions of the SOX9 promoter were consistently methylated in the proliferative phenotype melanoma cell cultures and consistently unmethylated in the invasive phenotype melanoma cell cultures." (PMID 25885555, 2015). "Conversely, knockdown of SOX9 in the invasive phenotype melanoma cells reduced the invasive capacity of the cells." (PMID 25885555, 2015). "This is in analogy to the upregulation of SOX9 mRNA previously observed in melanoma cells upon SOX10 knockdown." (PMID 25629959, 2015). "To validate that SOX9 is indeed regulated by DNA methylation, we treated the five proliferative phenotype melanoma cell cultures with 5 μM 5-Aza-2′-deoxycytidine (a DNMT inhibitor) for 72 h." (PMID 25885555, 2015). "While SOX10 expression and function has been well established in adult melanocytes, naevi, and melanoma tissue in human and mice, studies on SOX9 expression in melanocytic cells are controversial." (PMID 25629959, 2015). "In conclusion, SOX9 is an important gene involved in melanoma invasion and negatively impacts melanoma patient survival." (PMID 25885555, 2015). "In striking contrast to the increase in SOX10 expression, SOX9 expression levels were low in human melanocytes and further decreased with melanoma progression." (PMID 25629959, 2015).
melanoma (continued). "Transcriptional analysis of SOX9-overexpressing melanoma cells reveals enrichment in epithelial to mesenchymal transition (EMT) pathways." (PMID 25885555, 2015). "Hypergeometric distribution of the overlap of the SOX9 microarray with 10 melanoma cell culture array was significant (P <0.001)." (PMID 25885555, 2015). "This provides strong evidence that specific DNA methylation is the molecular mechanism that regulates SOX9 expression in melanoma." (PMID 25885555, 2015). "Of note, the anti-tumorigenic effect elicited by suppressing SOX10 was abolished by concomitant SOX9 inactivation both in human melanoma cells as well as in mice." (PMID 25629959, 2015). "SOX9 was reported to be expressed in cultured human melanocytes in vitro, human melanocytes in vivo, and in human melanoma." (PMID 25629959, 2015). "Among others, these data suggest that while SOX10 acts as an inhibitor of apoptosis in melanoma cells, SOX9 elicits a proapoptotic response." (PMID 25629959, 2015). "Our study identifies the structurally related transcription factors SOX10 and SOX9 as functionally antagonistic regulators of postnatal melanocyte and melanoma development." (PMID 25629959, 2015). "When SOX10 is inactivated, SOX9 becomes upregulated and induces cell cycle arrest and death in melanoma cells." (PMID 25629959, 2015). "The contribution of heterogeneity in the melanoma TCGA patient population would be one of the largest factors for the difference in gene signatures between our SOX9 microarray and TCGA RNAseq data." (PMID 25885555, 2015). "SOX9 expression, however, was found in only 41% (23/56) of the primary melanoma samples, in which it was expressed in a few scattered cells accounting for less than 10% of all melanoma cells." (PMID 25629959, 2015). "Indeed, in human melanoma cells, loss of SOX10 not only resulted in upregulation of SOX9 expression, but also in global transcriptional changes highly similar to the changes observed upon SOX9 overexpression, indicating that these factors appear to play opposing functions in melanoma." (PMID 25629959, 2015). "SOX9 is a transcription factor involved in neural crest specification and SOX9 overexpression in melanoma cell lines have been shown to induce cell cycle arrest in a p21 dependent manner." (PMID 25885555, 2015). "In concordance with previously published data on SOX9 in melanoma, we also see G1/G0 arrest when SOX9 is overexpressed along with increased invasion." (PMID 25885555, 2015). "Here we show that in contrast to Sox10, Sox9 appears to be expressed at very low levels only and is functionally not required in melanocyte stem cells, committed melanocytes, and melanoma cells." (PMID 25629959, 2015). "SOX9 was knocked down with siRNA, and then the invasive ability of two invasive phenotype melanoma cell cultures was measured: M080201 and M080310." (PMID 25885555, 2015). "Taken together, SOX9 is a gene that is regulated by DNA methylation and functionally, SOX9 mediates cell cycle progression, invasion, and metastasis in melanoma." (PMID 25885555, 2015). "To confirm that promoter DNA hypermethylation correlated with transcriptional silencing of SOX9, we assessed mRNA levels using real-time RT-PCR in the 10 melanoma cell cultures." (PMID 25885555, 2015). "Survival analysis of The Cancer Genome Atlas melanoma dataset shows that metastatic patients with high expression levels of SOX9 have significantly worse survival rates." (PMID 25885555, 2015). "In line with our results in cervical cancer, SOX9 has been shown to inhibit melanomas and endometrial tumors." (PMID 26036262, 2015). "Overexpression of SOX9 inhibits the growth and tumorigenicity of prostate cancer cells, attenuates melanoma cell growth, and restores sensitivity to retinoic acid treatments." (PMID 26384302, 2015). "We show that a transcription factor called SOX10 promotes melanoma formation by repressing an anti-tumorigenic program involving the activity of a related factor, SOX9." (PMID 25629959, 2015).